GRP (gastrin releasing peptide)
Diseases named in the same sentence as GRP in open-access papers (continued):
Sharing a sentence is not in itself a finding about the gene and the disease.
neuroblastoma (continued). "Indeed, p27kip is involved in GRP (gastrin‐releasing peptide)/GRP‐R pathway, whose inhibition increases p27kip expression levels in neuroblastoma cells." (PMID 28667701, 2017). "Mechanistically, GRP silencing resulted in upregulation of tumor suppressor PTEN with subsequent downregulation of critical oncogenes and proliferation/survival pathways implicated in neuroblastoma progression." (PMID 24039782, 2013). "GRP acts as a mitogen for a variety of cancers, including neuroblastoma." (PMID 24039782, 2013). "Lack of complete inhibition of primary tumor growth could be potentially due to a marginal reduction of the proliferative capacity of neuroblastoma cells after GRP silencing." (PMID 24039782, 2013). "Taken together, our results argue for a dual purpose of targeting GRP in neuroblastoma –1) decreasing expression of critical oncogenes involved in tumor progression, and 2) enhancing activation of tumor suppressor genes to treat aggressive, advanced-stage disease." (PMID 24039782, 2013). "Moreover, a role for GRP/GRP-R/AKT axis in the regulation of the MYCN oncogene in neuroblastoma is yet to be studied." (PMID 23468863, 2013). "Interestingly, PTEN overexpression decreased GRP-mediated migration and angiogenesis; a novel role for this, otherwise, understated tumor suppressor in neuroblastoma." (PMID 24039782, 2013). "Hence, our data indicate that GRP/GRP-R signaling regulates N-myc at a post-translational level in neuroblastoma cells." (PMID 23468863, 2013). "GRP binds to G-protein coupled receptor, GRP-R, to stimulate growth of a number of normal and neoplastic tissues of the gastrointestinal tract, including neuroblastoma." (PMID 23468863, 2013). "We also showed that BBS/GRP increases angiogenesis and primary neuroblastoma growth in vivo." (PMID 24039782, 2013). "Much is unknown about the downstream signaling pathways and target genes involved in GRP-mediated neuroblastoma progression." (PMID 24039782, 2013). "AKT2 plays an important role in human neuroblastoma cells as a downstream target of GRP/GRP-R and regulates neuroblastoma cell proliferation, anchorage-independent growth, migration and invasion in vitro, implicating AKT2 in multiple aspects of neuroblastoma initiation and progression." (PMID 23468863, 2013). "FAK inhibitor (Y15) suppressed GRP-induced neuroblastoma growth and metastasis." (PMID 23211542, 2012). "Thus, our in vivo data corroborate in vitro findings, and further suggest that FAK is an important regulator in GRP/GRP-R signaling pathway and tumor metastasis in neuroblastoma." (PMID 23211542, 2012). "In addition, similar to NETs, neuroblastomas can demonstrate amine precursor uptake and decarboxylation, as well as secrete numerous biologically active peptides/amine including vasoactive intestinal peptide, gastrin, catecholamines, serotonin, and GRP." (PMID 34539578, 2021). "Furthermore, in vitro migration of cancer cells and tubule formation by human umbilical vein endothelial cells (HUVECs) demonstrate that PTEN overexpression decreased GRP-mediated motility and angiogenesis in neuroblastoma potentially through decreased activation of AKT and/or FAK." (PMID 24039782, 2013). "Due to our prior knowledge that PTEN mRNA and protein expression is negatively impacted by GRP-R overexpression and that GRP treatment stimulates the PI3K/AKT pathway in neuroblastoma cells, we sought to determine whether GRP-mediated signaling regulates PTEN expression." (PMID 24039782, 2013). "GRP is reported to increase cytosolic calcium in neuroblastoma cell lines (SK-N-SH, LAN-2), and in LAN-1 neuroblastoma cells, the stimulation was inhibited by a specific GRPR antagonist." (PMID 34539578, 2021). "Among them, gastrin-releasing peptide (GRP), the mammalian equivalent of bombesin (BBS), has been shown to play a key role in the mitogenic potential of neuroblastoma cells." (PMID 24039782, 2013).
neuroblastoma (continued). "Our previous studies have demonstrated that PI3K/AKT signaling is critical for the oncogenic transformations induced by gastrin-releasing peptide (GRP) and its receptor, GRP-R, in neuroblastoma." (PMID 23468863, 2013). "Targeting GRP/GRP-R/AKT2 would be advantageous in developing a novel therapeutic option for aggressive and undifferentiated neuroblastomas with a high propensity for metastasis." (PMID 23468863, 2013). "Here, we show that GRP or BBS stimulates neuroblastoma cell migration as well as liver metastases, further supporting a critical tumorigenic role of GRP or BBS in neuroblastoma." (PMID 23211542, 2012). "GRP/GRP-R regulated FAK activation and expression, and further inhibition of FAK repressed GRP/GRP-R signaling involved in neuroblastoma progression." (PMID 23211542, 2012). "We and others have shown that GRP and BBS bind to GRP-R with high affinity to stimulate neuroblastoma cell growth in an autocrine and/or paracrine fashion." (PMID 23211542, 2012). "In one study, neither the expression level of GRP mRNA nor GRPR mRNA in the neuroblastoma tissue correlated with prognosis." (PMID 34539578, 2021). "In this study of GRP, immunoreactivity was also detected in 73% of the neuroblastomas, but in contrast to the GRPR, its expression was not affected by the tumor histology." (PMID 34539578, 2021). "Several studies have shown that GRP/GRP-R targeted therapy inhibits neuroblastoma tumor growth and both AR positive and negative PC tumors." (PMID 27542219, 2016). "We treated AKT2 silenced neuroblastoma cells with or without GRP (100 nM) for 2 h after serum-starvation overnight, and IGF-1 (100 nM) was used as positive control." (PMID 23468863, 2013). "In this report, we show that silencing of GRP signaling has a negative effect on the invasion-metastasis cascade in neuroblastoma cells." (PMID 24039782, 2013). "However, the molecular mechanism of GRP/GRP-R signaling regulation of Mycn and subsequently FAK in Mycn-amplified neuroblastoma cells or Mycn single copy neuroblastoma cells remain to be defined." (PMID 23211542, 2012). "However, in another study, the level of expression of GRPR mRNA, but not the amount of GRP mRNA, correlated with the histology of the neuroblastoma, with undifferentiated tumors having greater expression." (PMID 34539578, 2021). "Evidence also suggests that PI3K/Akt is activated downstream of Gastrin-Releasing Peptide (GRP)/Gastrin-Releasing Peptide Receptor (GRPR) and Brain-derived neurotrophic factor (BDNF)/TrkB signaling, which are reported to be overexpressed in human neuroblastoma." (PMID 26793165, 2015). "However, the intracellular signaling mechanisms involved in GRP/GRP-R-mediated FAK activation and subsequent neuroblastoma cell growth, motility and metastasis remain unclear." (PMID 23211542, 2012). "In IMR-32 neuroblastoma cells, GRP did not stimulate changes in cytosolic calcium, although it stimulated growth in these cells, suggesting both Ca2+-dependent and Ca2+-independent pathways may mediate the growth effects of GRPR activation in different neuroblastoma cells." (PMID 34539578, 2021). "However, whether GRP is involved in promoting metastasis and by what mechanism this may occur in neuroblastoma has not been answered." (PMID 24039782, 2013). "In another study, in tissues from 19 neuroblastomas, all had GRP mRNA and GRPR mRNA detected, although neither the amount of GRPR nor GRP mRNA correlated with prognosis." (PMID 34539578, 2021). "In IMR-32 neuroblastoma cells, GRP did not stimulate changes in cytosolic calcium, although GRP stimulated growth, suggesting both Ca2+-dependent and -independent pathways may mediate the growth effects of GRPR activation in different neuroblastoma cells." (PMID 34539578, 2021).
breast carcinoma (13 papers, 1999 to 2023). "Breast cancers express gastrin-releasing peptide (GRP) hormone and gastrin-releasing peptide receptor (GRP-R), and its expression is associated with lymph node metastases." (PMID 36832085, 2023). "GRP and Y1R are the most highly expressed peptide receptors in primary breast cancer, where they appear alone or in combination in more than 82% of resectable primary breast cancers." (PMID 34421823, 2021). "Expressions of the GRP proteins on MDA-MB-231 cell-induced breast cancer xenografted tumor lesions were confirmed by immunohistochemistry (IHC) staining." (PMID 30887136, 2019). "GRP/BN promotes breast cancer growth and progression; the occurrence of these high-affinity receptors in breast cancer has instigated the scientists to develop newer BN-based diagnostic agents." (PMID 30887136, 2019). "Gold nanorods functionalized with gastrin-releasing peptide (Bombesin) showed uptake via GRP receptor-mediated endocytosis with high binding affinity to breast cancer cells." (PMID 25071577, 2014). "In mice that were vaccinated with the GRP-fusion HG6 protein before inoculation of breast cancer cells (EMT-6), there was a 3-fold reduction in tumor size compared to that of the control groups (phosphate buffered saline or HSP65-vaccinated mice)." (PMID 21385454, 2011). "In this study, a recombinant chimeric protein vaccine (HG6) containing six tandem repeats of a GRP fragment (18 to 27 amino acids) fused to the 65-kDa heat shock protein (HSP65) was used to treat mice challenged with breast cancer." (PMID 21385454, 2011). "Nude mice bearing orthotopic xenografts of MDA-MB-435 breast cancers were treated with bombesin/GRP antagonists for 6 weeks." (PMID 14710236, 2004). "This study demonstrates the antiangiogenic effect of bombesin/GRP antagonists RC-3095 and RC-3940-II, and underscores their possible therapeutic application for treatment of breast cancers." (PMID 14710236, 2004). "Our findings confirm the merit of continued investigations of bombesin/GRP antagonists for the development of another approach to the management of breast cancer." (PMID 14710236, 2004). "Our results demonstrate that the treatment of MDA-MB-435 oestrogen-independent breast cancers with bombesin/GRP antagonists RC-3095 and RC-3940-II significantly decreased the expression of mRNA for VEGF-A, b-FGF and IGF-II, as well as their protein levels." (PMID 14710236, 2004). "We have investigated the production, growth and inactivation of gastrin-releasing peptide (GRP)-like peptides in human breast cancer cell lines." (PMID 9888460, 1999). "Bombesin is an analog of the mammalian gastrin-releasing peptide (GRP) and has demonstrated high sensitivity to detect the GRP receptor in breast cancer." (PMID 39355052, 2023). "Numerous pieces of evidence are supporting the role of gastrin-releasing peptide (GRP) in the initiation and progression of breast cancer." (PMID 35045088, 2022). "Breast cancer has been reported to express different types of peptide receptors, such as somatostatin, vasoactive intestinal peptide (VIP), gastrin-releasing peptide (GRP), and Y1R." (PMID 34421823, 2021). "Several lines of evidence indicate that mammalian bombesin-like peptide receptors, including the GRP and NMB receptors, are frequently overexpressed by a variety of tumor cell lines and tumor specimens from patients with lung, colorectal, gastric, prostate, and breast cancers." (PMID 24349381, 2013).
neuroendocrine tumors (12 papers, 2012 to 2026). "Moreover, patients with elevated pro-GRP levels are at high risk for neuroendocrine tumors, as evidenced by one patient in this series whose pathological result indicated LCNEC." (PMID 39015681, 2024). "A solitary pulmonary nodule was identified in the right upper lobe on preoperative chest CT, and the serum progastrin-releasing peptide (proGRP) level was markedly elevated, suggesting a neuroendocrine tumor." (PMID 42291913, 2026). "We further annotated tumor cells using four markers closely associated with neuroendocrine tumors: ASCL1, NCAM1, INSM1, and GRP." (PMID 40213972, 2025).
squamous cell carcinoma (11 papers, 2010 to 2025). A carcinoma arising from squamous epithelial cells. "Currently, carcinoembryonic antigen (CEA), neuron-specific enolase (NSE), cytokeratin 19 fragment (CYFRA21-1), pro-gastrin-releasing peptide (ProGRP) and squamous cell carcinoma (SCC) antigen are commonly used markers for the diagnosis of lung cancer." (PMID 34785692, 2021). "Gastrin-releasing peptide (GRP) signaling appears to mediate the autocrine growth of human squamous cell carcinoma of the head and neck." (PMID 32286381, 2020). "For example, squamous cell carcinomas typically produce parathyroid hormone-related proteins, and small cell carcinomas (SCC) of the lung typically produce calcitonin, adrenocorticotropin (ACTH), or gastrin releasing peptide (GRP)." (PMID 36620608, 2022). "Levels of tumor markers alpha-fetoprotein (AFP), carcinoembryonic antigen (CEA), carbohydrate antigen 19-9 (CA19-9), squamous cell carcinoma (SCC) antigen, pro-gastrin-releasing peptide (Pro-GRP), and prostate-specific antigen (PSA) were within the normal range." (PMID 33896422, 2021).
colon cancer (8 papers, 2012 to 2024). "Both STAC2 and NELL1 promoter CpG island hypermethylation has been reported in metastatic breast cancer and primary colon cancer, respectively and GRP is implicated in the development of tumorigenicity and drug resistance." (PMID 34922619, 2021). "Among them, TDGF, NRG1, and GRP have been demonstrated as prognostic indicators for patients with colon cancer." (PMID 35748788, 2022). "GRP signaling alters the invasion of colon cancer through heterochromatin protein 1Hsβ and can improve the prognosis of patients with colon cancer." (PMID 33167940, 2020). "One report showed that expression of FAK and phosphorylated (p)-FAK (Y397) correlates with the degree of colon cancer cell differentiation as well as to GRP/GRP-R co-expression." (PMID 23211542, 2012). "Gastrin-releasing peptide (GRP) may serve as an independent predictor of survival in patients with colon cancer." (PMID 36221049, 2022). "The over-expression of gastrin releasing peptide (GRP) and its receptor can be discovered after malignant transformation of colon cancer cells, and they can also enhance tumor attachment to the extracellular matrix and promote cytolysis of NK cells." (PMID 33996273, 2021).
non-small cell lung carcinoma (8 papers, 1994 to 2025). A group of at least three distinct histological types of lung cancer, including non-small cell squamous cell carcinoma, adenocarcinoma, and large cell carcinoma. "In comparison, the serum Pro-GRP level in the SCLC group was considerably higher than in the non-small cell lung cancer group." (PMID 37476198, 2023). "Among them, EGFR and pro-GRP are widely used in the diagnosis and evaluation of non-small-cell lung cancer." (PMID 36157204, 2022). "Other authors reported that GRP can induce Akt phosphorylation at Serine 473 in a non-small cell lung carcinoma cell line, and that this activation occurred through transactivation of the epidermal growth factor receptor (EGFR), a known Akt activator." (PMID 26097883, 2015). "Afatinib targeted therapy has a significant clinical intervention effect on patients with non-small-cell lung cancer, which not only helps to improve the immune function of patients but also effectively improves the serum EGFR and pro-GRP levels of patients." (PMID 36157204, 2022).
colorectal cancer (5 papers, 1995 to 2021). A primary or metastatic malignant neoplasm that affects the colon or rectum. "A Previous study shows that GRP can better predict the prognosis of patients with colorectal cancer and distant metastasis, and has good sensitivity and specificity." (PMID 29653552, 2018). "GRP expression may be a predictive of aggressive tumor biomarkers for stratifying stages of colorectal cancer." (PMID 31781593, 2019).
lung neuroendocrine neoplasm (5 papers, 2019 to 2025). A low, intermediate, or high grade malignant neoplasm with neuroendocrine differentiation that arises from the lung. "The aim of this study was to evaluate the diagnostic effectiveness of pro-gastrin-releasing peptide (ProGRP) and chromogranin A (CgA) in the diagnosis of neuroendocrine neoplasms of the lung (LNENs), (290 cases) and compared these results with controls (54 cases)." (PMID 37444393, 2023). "Comparisons of pulmonary neuroendocrine tumors (PNET) and other groups with ROC analysis in terms of progastrin-releasing peptide (ProGRP), neuron-specific enolase (NSE), adjusted NSE, chromogranin A (CgA), and squamous cell carcinoma antigen 1 (SCCA1) values." (PMID 31091854, 2019). "GRP expression was also found in human lung NETs, most published between 1983 and 2006, but was not compared with histology, subtype, or clinical features." (PMID 41196447, 2025). "Progastrin-releasing peptide (ProGRP), neuron-specific enolase (NSE), NSE adjusted, chromogranin A (CgA), and squamous cell carcinoma antigen 1 (SCCA1) values in the pulmonary neuroendocrine tumors (PNET), non-small-cell lung carcinoma (NSCLC), benign, and healthy groups." (PMID 31091854, 2019).
pancreatic cancer (5 papers, 2001 to 2024). "BB2, formerly known as GRPR, specifically binds to gastrin-releasing peptide (GRP) and is a promising option for directing and treating pancreatic cancer (PC)." (PMID 38496894, 2024). "Neuropeptides like bombesin, cholecystokinin, neuromedin N, neurotensin (NT), gastrin-releasing peptide and pituitary adenylate cyclase activating peptide stimulate growth and/or other cellular functions in various tumor types, including pancreatic cancer." (PMID 24212612, 2011). "In contrast to previous reports, the GRP and IGF-I receptors were shown not to be required for autocrine effects on pancreatic cancer cell proliferation." (PMID 11286473, 2001).
pulmonary fibrosis (5 papers, 2014 to 2025). Chronic progressive interstitial lung disorder characterized by the replacement of the lung tissue by connective tissue, leading to progressive dyspnea, respiratory failure, or right heart failure. "GRP also contributes to the pathogenesis of pulmonary fibrosis by stimulating proliferation of MRC5 fibroblast early on and their differentiation into myofibroblasts in the later period." (PMID 32552754, 2020). "GRP contributes to the pathogenesis of pulmonary fibrosis by stimulating the proliferation of MRC5 fibroblast cells at an early stage and their differentiation into myofibroblasts in the later on." (PMID 32552754, 2020). "We have determined that excessive GRP leads to lung injury with acute and chronic inflammation, leading to pulmonary fibrosis (PF), triggered via ROS exposure or by directly treating mice with exogenous GRP." (PMID 25101250, 2014). "Although this last study showed that GRP might modulate the pathogenesis of pulmonary fibrosis, the target cells and signalling pathways of GRP-mediated generation of fibrotic response were not investigated." (PMID 32552754, 2020). "In conclusion, GRP may lead to pulmonary fibrosis due to its proliferative and fibrotic effects on lung fibroblasts." (PMID 32552754, 2020). "Cumulatively, these studies provide the foundation for future exploration of how GRP could mediate lung injury including acute and chronic inflammation and pulmonary fibrosis (PF)." (PMID 25101250, 2014). "GRP was shown to induce the fibrotic response in a murine model of lung fibrosis and in human cell lines, and GRPR antagonism can reverse the effect of GRP on cell proliferation, indicating increased GRPR may be involved in the fibrotic response." (PMID 34912333, 2021).